U2 (U2 spliceosomal RNA )
Synonyms: LOC124904143
Gene: Small nuclear RNA gene on chromosome 17 (43,296,425 to 43,296,615, reverse strand). Ensembl gene ENSG00000275219.
Gene Ontology:
Molecular function: pre-mRNA branch point binding
Biological process: mRNA branch site recognition
Cellular component: U2 snRNP
Homologues: Orthologues: chimpanzee U2 (100% identical), macaque U2 (100% identical), dog U2 (99% identical), pig U2 (48% identical), rat LOC120094029 (36% identical). Paralogues in human: U2 (100% identical), RNU2-2 (96% identical), U2 (95% identical), RNU2-3P (93% identical), RNU2-4P (93% identical), RNU2-17P (90% identical), RNU2-6P (90% identical), RNU2-48P (89% identical), RNU2-52P (89% identical), RNU2-59P (89% identical), RNU2-25P (87% identical), RNU2-26P (87% identical), and 68 more.